SERPINA11 (serpin family A member 11)
Tractability: Antibody: UniProt places it where antibodies can reach, with high confidence; UniProt predicts a signal peptide or a membrane-spanning region; its Gene Ontology location is reachable by antibodies, with medium confidence.
Gene: Protein-coding gene on chromosome 14 (94,442,464 to 94,452,828, reverse strand). Ensembl gene ENSG00000186910.
Subcellular location: Secreted
Gene Ontology:
Molecular function: serine-type endopeptidase inhibitor activity
Cellular component: extracellular region
Genetic constraint (gnomAD): Loss-of-function variants: 29 observed, 31.91 expected, observed/expected ratio (o/e) 0.91, 90% interval 0.68 to 1.24. The upper end of that interval is the gene's LOEUF score, 1.24, which puts it in group 5 of 6, group 1 being the genes least tolerant of losing a copy. Missense variants: 530 observed, 527.25 expected, observed/expected ratio (o/e) 1.01, 90% interval 0.94 to 1.08. Synonymous variants: 253 observed, 216.36 expected, observed/expected ratio (o/e) 1.17, 90% interval 1.05 to 1.3.
Homologues: Orthologues: chimpanzee SERPINA11 (99% identical), macaque SERPINA11 (96% identical), pig SERPINA11 (82% identical), dog SERPINA11 (81% identical), rat Serpina11 (76% identical), mouse Serpina11 (75% identical), guinea pig SERPINA11 (75% identical). Paralogues in human: SERPINA4 (44% identical), SERPINA9 (43% identical), SERPINA1 (41% identical), SERPINA7 (41% identical), SERPINA3 (40% identical), SERPINA5 (38% identical), SERPINA6 (36% identical), SERPINA12 (32% identical), SERPINB4 (29% identical), SERPINB10 (28% identical), SERPINB1 (28% identical), SERPINB3 (28% identical), and 24 more.
Diseases named in the same sentence as SERPINA11 in open-access papers:
SERPINA11 is named in the same sentence as 8 diseases in open-access papers, as found by Europe PMC text mining. Sharing a sentence is not in itself a finding about the gene and the disease. The quoted sentences say what the papers report.
hepatocellular carcinoma (2 papers, 2025). A malignant tumor that arises from hepatocytes. "In pre- but and not postmenopausal tumors, the CC genotype harbored the increased expression of CSNS1, in which high expression has been associated with worse survival outcomes in BC and SERPINA11, which has been implicated in tumor suppression in hepatocellular carcinoma." (PMID 40565184, 2025). "Serpin family A member 11 (SERPINA11) is not a well-understood protein, but it can inhibit cell growth, cell migration, and tumor metastasis in hepatocellular carcinoma patients." (PMID 41614843, 2025).
Obesity (2 papers, 2013 to 2026). Accumulation of substantial excess body fat. "One group of genes (SERPINA12, CPE, SERPINA11, MTCH2, PNPLA5, INTS1, APOM) was associated (cosine value >0.1) with obesity and diabetes." (PMID 23544116, 2013). "Notably, Igfbp2 and Serpina11 were associated with pathways such as ‘Extracellular space’ in the broader RYGB-Induced analysis, suggesting potential roles in reshaping extracellular or signaling environments to reverse obesity-linked liver perturbations." (PMID 41598416, 2026).
type 2 diabetes (1 paper, 2020). "Although the roles of Serpina11, Cdh16, Lrrc27, and Lrrc66 in regulating islet function remain unclear, Acod1 is known to be important in modulating the immune system and mitochondrial function, and Fgf21 can protect against type 2 diabetes in mice by increasing insulin expression and secretion." (PMID 32527043, 2020).
tumor (3 papers, 2014 to 2025). "Additionally, we also found a slight indication that UBE2C and SCUBE2, SERPINA11, and NME5 were associated with tumor differentiation (P = 0.06 and P = 0.09, respectively), inflammatory infiltration (P = 0.09), and p16 expression (P = 0.08), respectively." (PMID 24885002, 2014).
SERPINA11 also shares sentences with these, for which no sentence is quoted: breast carcinoma (1 paper); diabetes (1); Ehlers-Danlos syndrome (1); invasive breast carcinoma (1).